RNU2-37P (RNA, U2 small nuclear 37, pseudogene)
Gene: Small nuclear RNA gene on chromosome 3 (128,075,073 to 128,075,249, reverse strand). Ensembl gene ENSG00000222627.
Homologues: Orthologues: chimpanzee U2 (99% identical), macaque U2 (96% identical), dog U2 (84% identical). Paralogues in human: U2 (92% identical), RNU2-3P (89% identical), RNU2-2 (88% identical), RNU2-4P (88% identical), U2 (88% identical), RNU2-17P (86% identical), RNU2-59P (85% identical), RNU2-52P (84% identical), RNU2-6P (84% identical), RNU2-25P (83% identical), RNU2-26P (83% identical), RNU2-64P (83% identical), and 67 more.